HMGA1 (high mobility group AT-hook 1)
Diseases named in the same sentence as HMGA1 in open-access papers (continued):
Sharing a sentence is not in itself a finding about the gene and the disease.
breast carcinoma (continued). "In accordance to this, we previously demonstrated that HMGA1 has a profound impact in the breast cancer cell secretome, inducing the release of a pool of pro-migratory proteins that act with an autocrine mechanism." (PMID 31311575, 2019). "KIFC1 expression was decreased in HMGA1-silenced breast cancer cells, while HMGA1 was decreased in KIFC1 knockdown HCC cells in our study." (PMID 31340839, 2019). "Among the genes, CCNE2, which has been connected to the migratory ability of tumoral cells, has been proved to be under the transcriptional control of HMGA1, thus promoting the migratory and invasive abilities of breast cancer cells." (PMID 31311575, 2019). "Here we made use of atomic force microscopy to analyze the stiffness of breast cancer cellular models in which we modulated HMGA1 expression to investigate its role in regulating nuclear plasticity." (PMID 31167352, 2019). "It has been reported that HMGA1 plays anti-apoptotic role by modulating BCL2 in human breast carcinoma cells." (PMID 29581847, 2018). "Only recently, HMGA-1 (High-mobility group protein A1) a structural chromatin protein was shown to be involved in cancer and its invasiveness in breast cancer." (PMID 30486335, 2018). "HMGA1 has a driving role in breast cancer development, however, its contribution in modulating the abundance of proteins acting in the extra–cellular milieu and/or involved in cell/cell communication is still almost unexplored." (PMID 28924209, 2017). "Performing an iTRAQ LC–MS/MS screening for the identification of secreted proteins, in an inducible model of HMGA1 silencing in breast cancer cells, we found that HMGA1 has a profound impact on cancer cell secretome." (PMID 28924209, 2017). "First, we searched for articles that mentioned the predicted miRNA- mRNA pairs in the corresponding cancer type, e.g., let-7a-5p-HMGA1 in breast cancer." (PMID 29042600, 2017). "HMGA1 overexpression has a prominent role in breast cancer progression by reprogramming cancer cells to a stem-like state and conferring them aggressiveness, both in term of cell migration, invasion, and metastatic capabilities." (PMID 28924209, 2017). "The function of HMGA1 in regulating metastatic progression has been described in colon and breast cancers." (PMID 28290473, 2017). "In regards to breast cancer, several experimental results have assigned a critical role for HMGA1 in driving breast cell transformation." (PMID 26527623, 2016). "The overexpression of HMGA1 has been observed in several malignant neoplasias, such as thyroid cancer, colon cancer, breast cancer, lung cancer, ovarian cancer and prostate carcinoma, as well as head and neck tumors." (PMID 25572132, 2015). "Our study, together with data from previous studies, provides compelling evidence of the crucial role of HMGA1 in breast cancer progression." (PMID 25572132, 2015). "These tissue microarray data suggest that a differential expression of HMGA1 exists in various types of breast cancer." (PMID 25572132, 2015). "To further unravel the significance of HMGA1 in clinical prognosis, we detected the expression of HMGA1 in a tissue microarray containing 159 breast cancer cases and 32 breast tumor adjacent tissues." (PMID 25572132, 2015). "Transforming growth factor-β1 (TGF-β1) signaling and high mobility group A (HMGA1) are known to play essential roles in the progression of breast cancer by inducing epithelial-mesenchymal transition." (PMID 25572132, 2015). "It was found that 76% of the ductal breast cancer cases showed HMGA1 positive staining and 90% of the paired lymph node samples showed an expression of HMGA1, although statistical analysis showed no significance (P=0.088)." (PMID 25572132, 2015). "Taken together, these results suggest that CCNE2 plays a specific role in promoting cell migration and invasion in metastatic breast cancer cell lines downstream of HMGA1." (PMID 26265440, 2015).
breast carcinoma (continued). "The tissue microarray analysis revealed that HMGA1 was expressed in 62.3 and 46.9% of the breast tumor tissues and matched breast cancer adjacent tissues, respectively, predominantly in the nucleus." (PMID 25572132, 2015). "We recently showed that HMGA1 promotes metastatic processes in basal-like breast cancer cells by regulating the EMT and stemness via the activation of a specific gene signature." (PMID 26265440, 2015). "Recent studies aiming at silencing HMGA1 expression by delivery of short hairpin (sh)RNAs reported an attenuated growth and major changes in appearance of breast cancer cells upon HMGA1 knockdown." (PMID 26117853, 2015). "Among those genes, we found that CCNE2 acts downstream of HMGA1 to mediate breast cancer metastasis." (PMID 26265440, 2015). "In this study, we aimed to determine the effects of TGF-β1 on the expression of HMGA1 in breast cancer cells." (PMID 25572132, 2015). "Based on the analysis of a breast cancer meta-dataset, we detected a strong correlation between the HMGA1 and CCNE2 expression levels (linear regression model, P < 10−15)." (PMID 26265440, 2015). "In this study, we determined the effects of TGF-β1 on HMGA1 expression in breast cancer cells and examined the role of HMGA1 in breast cancer progression." (PMID 25572132, 2015). "The effects of HMGA1 on cell migration and invasion, properties of breast cancer progression, were further assessed and it was observed that the ectopic expression of HMGA1 in the MCF-7 cells markedly promoted cell migration and invasion." (PMID 25572132, 2015). "Here, we show that cyclin E2 (CCNE2) acts downstream of HMGA1 to regulate the motility and invasiveness of basal-like breast cancer cells by promoting the nuclear localization and activity of YAP, the downstream mediator of the Hippo pathway." (PMID 26265440, 2015). "Silencing of HMGA1 using a specific siRNA caused significant down-regulation of CCNE2 expression at both the mRNA and protein levels in the MDA-MB-231 and MDA-MB-157 breast cancer cell lines." (PMID 26265440, 2015). "We further determined the downstream key molecules in the PI3K signaling pathway which mediate the TGF-β1- induced expression of HMGA1 in breast cancer cells." (PMID 25572132, 2015). "Ongoing studies have analyzed HMGA1 expression in breast carcinomas by using a tissue microarray (TMA) containing more than 1000 carcinoma samples, mainly ductal histotype, complete for the follow-up." (PMID 25859543, 2015). "In breast cancer cells, HMGA1 is primarily involved in regulating cell motility and invasiveness; however, its downstream effectors are not well characterized." (PMID 26265440, 2015). "Sp1 has previously been confirmed to be an essential modulator of the regulation of HMGA1 promoter activity and we determined the involvement of Sp1 in the TGF-β1-induced HMGA1 expression in breast cancer cells." (PMID 25572132, 2015). "Then, we stratified breast cancer samples according to their relative expression levels of HMGA1 and CCNE2, obtaining a significant difference in patient distribution (chi-square, P < 10−15)." (PMID 26265440, 2015). "Deregulation of the HMGA1 expression was described in human PC, lung cancer, and breast cancer cells." (PMID 25276782, 2014). "The results of our study not only suggest that HMGA1 plays a critical role in breast cancer aggressiveness but also provide strong evidence for the action of HMGA1 in basal-like breast tumours." (PMID 23945276, 2013). "Similar results were obtained after HMGA1 depletion in another basal-like breast cancer cell line, MDA-MB-157." (PMID 23945276, 2013). "Together, these findings indicate that HMGA1 is a master regulator of tumor progression in breast cancer by reprogramming cancer cells through stem cell transcriptional networks." (PMID 23658826, 2013). "In fact, silencing HMGA1 in highly metastatic breast cancer cell lines impaired mesenchymal fibroblastoid features." (PMID 23945276, 2013).
breast carcinoma (continued). "We demonstrated that HMGA1 plays a pivotal role in regulating invasive processes and determining poor prognostic outcomes in breast cancer by sustaining the mesenchymal phenotype and stemness." (PMID 23945276, 2013). "In the present study, we show that the High Mobility Group A1 (HMGA1) protein plays a fundamental role in this process in basal-like breast cancer subtype." (PMID 23945276, 2013). "Taken together, these data provide new insights into the role of HMGA1 in the acquisition of aggressive features in breast cancer." (PMID 23945276, 2013). "The overlap between the YB-1 and HMGA1 gene signatures further illustrates the fact that HMGA1 is involved in breast cancer aggressiveness that is mediated by EMT and stem cell processes." (PMID 23945276, 2013). "To define an HMGA1 signature in breast cancer, we identified the 100 transcripts that were most differentially expressed." (PMID 23658826, 2013). "Silencing HMGA1 expression in invasive, aggressive breast cancer cells dramatically halts cell growth and results in striking morphologic changes from mesenchymal-like, spindle-shaped cells to cuboidal, epithelial-like cells." (PMID 23658826, 2013). "Overall, these results clearly demonstrate that HMGA1 depletion reverses the transformed phenotype of breast cancer cells, indicating potential regulation of the mesenchymal to epithelial transition (MET) by HMGA1." (PMID 23945276, 2013). "Using bioinformatic analyses, we demonstrated that HMGA1 is overexpressed in the breast cancer subtypes that carry poor prognoses and tend to metastasise." (PMID 23945276, 2013). "Here, we report for the first time that silencing HMGA1 induces a rapid and dramatic reprogramming of highly proliferative, invasive, mesenchymal-like breast cancer cells to more differentiated, slowly growing, epithelial-like cells." (PMID 23658826, 2013). "These preliminary in vivo results provide evidence of the active regulation of metastatic processes in breast cancer by HMGA1." (PMID 23945276, 2013). "High HMGA1 protein levels correlate with poor differentiation in pancreatic and breast cancers and decreased survival in pancreatic and lung cancers by immunohistochemical analysis in primary tumors." (PMID 22053823, 2011). "HMGA1 also promotes metastatic progression and an epithelial-to-mesenchymal transition in a breast cancer model." (PMID 22053823, 2011). "For example, HMGA1 protein expression indicates adverse clinical outcomes in breast cancer." (PMID 38405614, 2024). "However, another study reports that breast cancer cells overexpressing HMGA1 exhibit a faster recovery upon induction of DNA double-strand breaks (DSBs), indicating a potentially controversial role for HMGA1 in DNA damage repair." (PMID 39769030, 2024). "HMGA1 is a protein that has been found to play a role in the progression of breast cancer." (PMID 39040191, 2024). "In addition, serum-starvation treatment significantly impaired the interaction between YB1 and HMGA1 mRNA in breast cancer cells." (PMID 37035211, 2023). "Moreover, HMGA1 was obviously higher in basal-like breast cancer than in the other subtypes, which dictated therapeutic guidance and portended prognosis." (PMID 36479041, 2022). "It was worth mentioning that HMGA1 expression was obviously lower in luminal A BC than in the other subtypes in cohort from both bc-GenExMiner and cBioportal, and it was obviously higher in basal-like breast cancer than in the other subtypes." (PMID 36479041, 2022). "Finally, we explored the role of HMGA1 silencing on proliferation, apoptosis, migration, and invasion in breast cancer cells." (PMID 36479041, 2022). "In addition, we utilized functional and pathway enrichment analysis to explore the potential mechanisms of HMGA1 in breast cancer." (PMID 36479041, 2022).
breast carcinoma (continued). "In addition, breast cancer and neuroblastoma cell line experiments showed that inhibition of HMGA1 reduces the performance of pErk, affecting tumor cell proliferation, migration, and invasion, and increasing apoptosis." (PMID 35629376, 2022). "Additionally, high HMGA1 expression was observed in breast cancer in the TCGA cohort compared to normal breast tissues." (PMID 36479041, 2022). "However, the prognostic value of HMGA1 in breast cancer tissues and the mechanism in tumor progression remain to be determined." (PMID 36479041, 2022). "Higher HMGA1 predicted poor survival in breast cancer patients." (PMID 36479041, 2022). "We focused on HMGA1, a transcription factor that is known to bind to AT-rich sequences/regions and transactivate several cell cycle and DNA repair genes that showed reduced expression in CB-treated breast cancer cells." (PMID 35610507, 2022). "Therefore, we further assessed the impact of HMGA1 on PI3K/AKT/MMP-9 pathway in breast cancer cells." (PMID 36479041, 2022). "Our findings indicate that HMGA1 may be a critical prognostic indicator and potential therapeutic target of breast cancer." (PMID 36479041, 2022). "CD44 and HMGA1 are well-known markers of CSCs in breast cancer." (PMID 35611554, 2022). "However, the specific function and mechanism of HMGA1 still need further exploration in breast cancer." (PMID 36479041, 2022). "HMGA1 is frequently overexpressed in various human malignancies, including breast cancer and CCA." (PMID 34716319, 2021). "For example, the levels of HMGA1 was highly expressed in breast cancer tissues." (PMID 34167089, 2021). "Similarly, RAD51 was downregulated in breast cancer cell line MDA-MB-231 upon HMGA1 depletion (GSE35525)." (PMID 34716319, 2021). "HMGA1 sensitizes breast cancer cells to cisplatin by downregulating the expression of BRCA1." (PMID 34716319, 2021). "Moreover, miR-625 has been revealed to suppress cell proliferation and migration by targeting HMGA1 in breast cancer." (PMID 34090483, 2021). "In addition, in a lung adenocarcinoma cell line, the overexpression of miR-26a inhibits cell migration and invasion by targeting HMGA1; miR-625 represses proliferation and migration by targeting HMGA1 in breast cancer cells." (PMID 31963852, 2020). "Indeed, it has been extensively demonstrated that these miRNAs are able to target HMGA1 gene in osteosarcomas, lung adenocarcinomas, bladder cancers, breast cancers, pituitary tumors." (PMID 32344629, 2020). "As an example, overexpression of HMGA1 leads to EMT in basal-like breast cancer cell." (PMID 31963852, 2020). "Our data indicate that HMGA1 could modulate the activity of these factors also in breast cancer progression, bringing to light common crucial HMGA1-oncogenic pathways in different cancer types." (PMID 31311575, 2019). "Some study also showed that miR-625 and let-7i could suppresses cell proliferation and migration by targeting HMGA1 in breast cancer." (PMID 31196036, 2019). "HMGA1 is defined as an oncofetal protein due to its expression pattern: indeed, it is highly expressed during embryogenesis, while its expression decreases or is absent in adults; it is then re-expressed in a variety of tumors, including breast cancer." (PMID 31311575, 2019). "Albeit at a speculative level, HMGA1 could be one of the chromatin factors cooperating with YB-1 in breast cancer onset and development." (PMID 31382504, 2019). "Liu also found that down-regulation of let-7a could inhibits growth and migration of breast cancer cells by targeting HMGA1." (PMID 31196036, 2019). "In addition, we showed that a set of HMGA1-dependent genes constitute a molecular signature with prognostic value in breast cancers and HMGA1 expressing cells secreted glycosylated factors involved in modulating cell motility and invasiveness." (PMID 31382504, 2019).
breast carcinoma (continued). "Here, we provide evidences that in breast cancer cells HMGA1 affects nuclear stiffness and that this effect could be, at least in part, explained through a mechanism involving histone H1, a protein linked to higher-order chromatin compaction." (PMID 31167352, 2019). "Indeed, in breast cancer patients a profound molecular relation between HMGA1, FOXM1 and VEGFA has been further highlighted by TCGA analysis, which confirmed a strong enrichment of VEGFA in patients that overexpressed HMGA1 and FOXM1." (PMID 31311575, 2019). "In our research, we demonstrated that the over-secretion of HMGA1 by invasive breast cancer cells could somehow mediate the invasive phenotype of these cells." (PMID 31779212, 2019). "The over-secretion of HMGA1 by invasive breast cancer cells opens the possibility that HMGA1 establishes new molecular interactions in the extracellular space that could complement its function as a transcriptional regulator in tumor cells." (PMID 31779212, 2019). "In breast cancer, the levels and subcellular localization of HMGA1 could be also useful to evaluate the antitumor efficacy and monitor the response to a specific therapy in TNBC patients." (PMID 31779212, 2019). "Given the difficulty of specifically targeting HMGA1 in breast cancer, we suggest that HMGA1 expression could steer the choice of therapeutic approaches towards epigenetic–targeting options." (PMID 31382504, 2019). "In breast cancer, miR-625-5p suppressed cell proliferation and migration by targeting HMGA1." (PMID 30988674, 2019). "Therefore, the possibility to target HMGA1/FOXM1 in combination should represent an attractive therapeutic option to counteract breast cancer angiogenesis." (PMID 31311575, 2019). "Moreover, the evaluation of this function in other breast cancer subtypes and even in additional cancer types, including colorectal, pancreatic, and ovarian, in which HMGA1 is also highly expressed, merits additional investigation." (PMID 31779212, 2019). "The main aim of our work was to systematically unravel the HMGA1 impact on breast cancer secretome in order to determine whether HMGA1 could influence cancer aggressiveness by the modulation of secreted proteins." (PMID 28924209, 2017). "Moreover, an alteration of HMGA1 expression levels leads to relevant changes in the tumorigenic properties of breast cancer cell lines." (PMID 26527623, 2016). "Moreover, breast cancer cells overexpressing HMGA1 show a faster recovery upon induction of DNA double-strand breaks, which is associated with a higher survival." (PMID 27723831, 2016). "HMGA1 proteins exploit pleiotropic mechanisms to drive breast cancer development and progression." (PMID 26527623, 2016). "Then, we investigated whether HMGA1P7 functions as ceRNA through, or partially through H19, IGF2 and HMGA1 in breast cancer human cells." (PMID 27874091, 2016). "Moreover, when we classified patients according to grade and molecular subtype, we found concurrently elevated expression of both CCNE2 and HMGA1 in Grade 3 breast cancer and in the more aggressive breast cancer subtypes (luminal B and basal-like)." (PMID 26265440, 2015). "The present study provides evidence of a link between TGF-β1 and HMGA1 in breast cancer cells." (PMID 25572132, 2015). "We recently identified a 130 gene-signature that is regulated by HMGA1 in breast cancer." (PMID 26265440, 2015). "In conclusion, to the best of our knowledge, the present study provides the first evidence of the role of TGF-β1 in the regulation of HMGA1 expression in breast cancer cells and PI3K signaling and Sp1 were found to be involved in the TGF-β1-induced expression of HMGA1." (PMID 25572132, 2015). "This study also offers further evidence of the pivotal role of HMGA1 in breast cancer progression." (PMID 25572132, 2015).